CASP8 (caspase 8)
Diseases named in the same sentence as CASP8 in open-access papers (continued):
Sharing a sentence is not in itself a finding about the gene and the disease.
cervical carcinoma (43 papers, 2006 to 2025). A carcinoma arising from either the exocervical squamous epithelium or the endocervical glandular epithelium. "For instance, the polymorphism of CASP8 – CASP8-652 6N ins/del in cervical cancer, which plays a role in HPV persistence, has been found in high frequencies in the African population and low in the Asian population." (PMID 40313245, 2025). "Combining BAY1251152 with Cisplatin synergistically overcame chemoresistance of Caspase-8-deficient cervical cancer cells." (PMID 36399280, 2022). "In the present study, we have demonstrated that Caspase-8 expression is frequently down-regulated in cervical cancer patients with high Tumor Mutational Burden (TMB), correlating significantly with poor prognosis." (PMID 36399280, 2022). "Meanwhile, polymorphisms in FASR-670A and CASP8-652 were associated with a reduced risk of developing cervical cancer in South African women." (PMID 33659210, 2020). "In this study, we found that the transfected HPV16 E6 can downregulate the increasing activation of caspase-8 caused by Daxx transfection in cervical cancer C33A cells." (PMID 32782452, 2020). "In the present study, we set out to investigate the combined risks of CASP8, FasR, and FasL polymorphisms in cervical cancer, pre-cancerous lesions, HPV infection and HSV-2 infection." (PMID 26458812, 2015). "The combined risks of CASP8 -652 6 N del + FasR-670A polymorphism showed a reduced risk of cervical cancer even when combined with FasR-1377 and FasL-844 polymorphisms." (PMID 26458812, 2015). "In the same population, a marginal susceptible risk to cervical cancer was also observed when CASP8 -652 6 N ins was combined with FasR-1377 G allele (P = 0.047, CPS = 1.99)." (PMID 26458812, 2015). "In another cDNA library screening experiment, 5×105 clones from a HeLa cervical carcinoma cDNA library were screened, resulting in 19 positives, of which 7 encoded a splice-variant of Caspase-8." (PMID 19876397, 2009). "Out of the 30 known genes associated with cervical cancer, only nine were studied in the African population (Caspase 8, Chemokine receptor 2, Fas cell death receptor, human leukocyte antigen, Interferon-gamma, interleukin 10, TP 53 Tumor necrosis factor-alpha, Transforming growth factor-beta 1)." (PMID 40313245, 2025). "Furthermore, the loss of Caspase-8 expression promotes migration and invasion in patient-derived cervical cancer cells, suggesting a correlation between Caspase-8 expression and elevated cervical tumor malignancy and aggression." (PMID 36399280, 2022). "However, when stratified among only black Africans a new reduced risk for cervical cancer was observed with CASP8 -652 6 N del combined with FasR-670 A allele (P = 0.019, CPS = −2.34)." (PMID 26458812, 2015). "The present study showed a reduced risk to cervical cancer combining CASP8 -652 6 N del with FasR-670 A allele (P = 0.019, CPS = −2.34) and a marginal susceptible risk to cervical cancer with CASP8 -652 6 N ins + FasR-1377G (P = 0.047, CPS = 1.99), only in black Africans." (PMID 26458812, 2015). "We therefore re-analysed our data evaluating the combined risks of CASP8 polymorphism in the presence of both FasR and FasL polymorphisms, on cancer of the cervix susceptibility, HPV infection and HSV-2 infection in South African women of black African and mixed-ancestry origin." (PMID 26458812, 2015). "Caspase-8 and -9 are implicated in the apoptotic effect of celecoxib in cervical cancer cells." (PMID 23675041, 2007). "None of the combinations of the polymorphisms had any significant association with cancer of the cervix in both populations combined and also when stratified for mixed-ancestry population, which is in accordance with our previous individual results with FasR/FasL and CASP8 polymorphisms." (PMID 26458812, 2015). "In our earlier observations in cervical cancer patients with higher Tumor Mutational Burden (TMB), the expression of CASP8 was also of prognostic relevance." (PMID 38201534, 2023).
cervical carcinoma (continued). "In summary, these data highlighted that the correlation between low CASP8 expression and the prognosis of cervical cancer patients depends on their TMB status." (PMID 36399280, 2022). "Further, the knock-out/attenuation of caspase-8 resulted in a significant enhancement of 2D cell migration and 3D cell invasion in favor of the involvement of caspase-8 in the regulation of transcriptional metastases in cervical cancer." (PMID 36428594, 2022). "Very limited information is available about the expression and functions of Caspase-8 in cervical cancer, although its activity decreases gradually as the malignancy progresses." (PMID 36399280, 2022). "Ultimately, our recent translational investigations have revealed that caspase-8 knockout cancer cells and cervical cancer lines are more resistant to the small-molecule CDK9 inhibitor BAY1251152 in both 2D and 3D spheroid culture conditions." (PMID 36428594, 2022). "The results of the previous experiments raised a fundamental question on how Caspase-8 alters the migration and invasion of cervical cancer cells." (PMID 36399280, 2022). "We have, thus far, demonstrated that low Caspase-8 expression in cervical cancer cell lines and primary tumors leads to higher CDK9 kinase activity." (PMID 36399280, 2022). "To determine the significance of Caspase-8 expression in the prognosis of cervical cancer patients, we splitted the patients from the CESC-TCGA database, based on their RNA-Seq data, into those with TMB lower or higher than the median." (PMID 36399280, 2022). "This strongly suggests that Caspase-8 plays a crucial role in undermining metastasis-promoting pathways in cervical cancer." (PMID 36399280, 2022). "Our work so far has demonstrated a direct correlation between Caspase-8 expression and pCDK9 levels in cervical cancer cell lines." (PMID 36399280, 2022). "This renders CDK9 a promising molecular target for treating cervical cancer patients with low Caspase-8 expression." (PMID 36399280, 2022). "To investigate this, we performed IHC staining of pre-treatment biopsies from 69 cervical cancer patients (FIGO IB–IVA) for Caspase-8 and pCDK9." (PMID 36399280, 2022). "We discovered that low Caspase-8 expression is associated with poor OS and PFS in cervical cancer patients." (PMID 36399280, 2022). "Knock-out and RNAi of Caspase-8 expression in cervical cancer cell lines enhanced cell-migration and cell-invasion by altering the RNAPII-mediated transcription of genes that regulated these functions." (PMID 36399280, 2022). "In summary, these data validated that, in cervical cancer patients, low or high Caspase-8 expression significantly correlated with increased or decreased pCDK9 levels and, by extension, phospho-RNAPII levels, respectively." (PMID 36399280, 2022). "CAR mediates the activation of caspase-9 and -3 (intrinsic pathway) and caspase-8 (extrinsic pathway) accompanied by the cleavage of PARP in cervical cancer cells." (PMID 36712982, 2022). "In previous studies by our group, low caspase-8 expression predicted unfavorable survival in anal and cervical cancer patients." (PMID 36428594, 2022). "In summary, we have confirmed that CDK9 interacts with the p12 domain of Caspase-8 within the nucleus of cervical cancer cells." (PMID 36399280, 2022). "The correlation between Caspase-8 expression and pCDK9 level was also observed in a cohort of cervical cancer primary materials." (PMID 36399280, 2022). "Cisplatin in combination with death receptor ligands enhances the expression of CASP8 in the HPV 16-positive cervical cancer cell line SiHa to increase apoptosis." (PMID 35070983, 2021). "Against this background, the prognostic impact of both PLK3 and pT273 Caspase-8 was investigated in patients with cervical cancer." (PMID 34830902, 2021).
cervical carcinoma (continued). "We also show that caspase-8 activity relies on the Daxx–JNK signal pathway, which will help elucidate the role of Daxx in the occurrence and development of cervical cancer with associated HPV16 infection." (PMID 32782452, 2020). "For example, IFN-β-mediated death of human cervical carcinoma cells can be through changes in the caspase-8/cFLIP balance in the death-inducing signaling complex (DISC)." (PMID 32106552, 2020). "The results suggest that ACE has potent and selective cytotoxic effect against cervical cancer cells and the potential to induce bax and caspase-8-dependent apoptosis." (PMID 31118873, 2019). "TMS-TMF-4f increased cleaved PARP, caspase-3, caspase-8, and caspase-9 in a concentration-dependent manner in human cervical cancer cells." (PMID 31816985, 2019). "In summary, our data support the notion that increased pre-treatment tumor levels of PLK3 and pT273 caspase 8 predict for superior clinical response among cervical cancer patients treated with definitive CRT plus BT." (PMID 31475104, 2019). "Here, we describe the association between disease-related outcomes and pre-treatment tumor PLK3 and pT273 Caspase 8 detection among locally-advanced cervical cancer patients." (PMID 31475104, 2019). "The activity of caspase 3, caspase 8, and caspase 9 was decreased in cisplatin-resistant cervical cancer cells." (PMID 28842515, 2017). "One recent study of 228 cervical cancers using TCGA data identified SHKBP1, ERBB3, CASP8, HLA-A, and TGFBR2 as novel significantly mutated genes, and previously identified pathogenic genes including PIK3CA, EP300, ARID1A, and NFE2L2 were also confirmed." (PMID 28390392, 2017). "No studies to date have attempted to find out the combined risks of all the four polymorphisms from FasR (−1377G > A, −670A > G), FasL (−844 T > C) and CASP8 (−652 6 N ins/del) genes on cervical cancer, HPV infection or HSV-2 infection in any population." (PMID 26458812, 2015). "Taken together, these results indicated that Mith induced mitochondria-mediated apoptosis through a DR5/caspase-8/Bid signaling pathway in cervical cancer cells." (PMID 25418289, 2014). "At the molecular level, Mith dramatically induced proteasome-dependent Sp1 degradation, thereby suppressing growth of cervical cancer cells through a DR5/caspase-8/Bid signaling pathway." (PMID 25418289, 2014). "Here, we show that Mith decreased Sp1 protein by inducing proteasome-dependent degradation, thereby suppressing cervical cancer growth through a DR5/caspase-8/Bid signaling pathway." (PMID 25418289, 2014). "At the molecular level, Mith dramatically induced Sp1 degradation in a proteasome-dependent manner and suppressed growth of cervical cancer cells through a DR5/caspase-8/Bid signaling pathway." (PMID 25418289, 2014). "Triptolide was demonstrated to induce apoptosis in cervical cancer cells and malignant schwannoma cells accompanied with caspase-8/9/3 and PARP cleavage, indicating the activation of the two apoptotic pathways." (PMID 24244715, 2013). "In our prior work, we substantiated that in cervical cancer patients exhibiting a high Tumor Mutational Burden (TMB), diminished Caspase-8 expression was associated with a dismal prognosis and resistance to conventional chemotherapeutic agents, specifically Carboplatin and Cisplatin." (PMID 38201534, 2023). "In addition, the knock-down of Caspase-8 expression in cervical cancer patient-derived cells also led to a significant increase in their invasiveness compared to non-transfected (NT) or siCtrl transfected cells." (PMID 36399280, 2022). "Inhibition of CK2 by DRB or overexpression of CK2α demonstrated that the activity of CK2 uncoupled Bid cleavage from caspase-8 activation in individual HeLa cervical cancer cells, leading to the conclusion that CK2 provides transient tolerance to caspase-8 activities." (PMID 36009534, 2022).
cervical carcinoma (continued). "To investigate whether the correlation between Caspase-8 expression and pCDK9 levels in cervical cancer patients also extended to phospho-RNAPII levels, we next knocked-down Caspase-8 expression in primary cells derived from a cervical tumor." (PMID 36399280, 2022). "As a result, loss of caspase-8 may lead to the hyperactivated state of CDK9, altering the transcriptional landscape of cervical cancer towards a more aggressive phenotype." (PMID 36428594, 2022). "Limited information is available on the expression patterns and functions of caspase-8 in cervical cancer, but there is evidence that caspase-8 activity gradually decreases from cervical intraepithelial neoplasia (CIN) to invasive cancer, which has been reported previously for other malignancies." (PMID 36428594, 2022). "As several third-generation CDK9 inhibitors such as AZD-4573, BAY1251152 and JSH-150 are currently undergoing clinical trials, our findings emphasize CDK9 as a promising molecular target for treating cervical cancer patients, especially those with low caspase-8 expression." (PMID 36428594, 2022). "One of the largest cervical cancer sequencing efforts—The Cancer Genome Atlas (TCGA) Project—reveals novel mutations in several genes, including SHKBP1, ERBB3, CASP8, HLA-A and TGFBR2, amplifications in immune targets PD-L1 and PD-L2, by sequencing 228 primary cervical cancer patients." (PMID 35205332, 2022). "Work on cervical cancer cell lines revealed that Caspase-8, located in their nuclear fractions, could directly interact with and inhibit the phosphorylation of CDK9 at Thr186." (PMID 36399280, 2022). "Similarly, our investigation of a cohort of primary cervical cancer patient-derived tissues also confirmed a significant correlation between high Caspase-8 expression and low CDK9 Thr186 phosphorylation, and low RNAPII Ser2 phosphorylation." (PMID 36399280, 2022). "The negation of mdivi-1 activation of CASP8 by TUFM depletion and the efficacy of TUFM depletion alone on CASP8 activation in the context of these cervical cancer cells provides further evidence that TUFM functions to promote mitophagy and prevent the accumulation of damaged mitochondria." (PMID 34511600, 2022). "However, stringent assessment and stratification of patients with high and low caspase-8 expression levels will be critical to evaluate the clinical success of future CDK9-based targeted strategies in cervical cancer and other tumor entities." (PMID 36428594, 2022). "In addition, by enhancing exogenous and endogenous apoptotic pathways, cisplatin amplifies CASP8 activation, sensitizing cervical cancer cells to apoptosis induced by rosulumab." (PMID 35070983, 2021). "Previous studies have shown that cisplatin acts on CASP8 in cervical cancer." (PMID 35070983, 2021). "PIK3CA (phosphatidylinositol-4,5-bisphosphat-3-kinase, catalytic subunit alpha), PTEN and MPK1 (mitogen-activated protein kinase 1) were confirmed as significantly mutated genes (SMG), while ERBB3, CASP8, HLA-A and TGFBR were identified as novel SMGs in cervical cancer." (PMID 34830902, 2021). "For instance, cisplatin could up-regulate expressions of Fas and FasL, activate caspase 8 pathways and induce apoptosis in uterine cervix cancer cells." (PMID 20470393, 2010). "Thus, we wondered whether targeting CDK9 would improve the response to Cisplatin-based chemotherapy in Caspase-8 KO cervical cancer cells." (PMID 36399280, 2022).
cervical carcinoma (continued). "Furthermore, our translational work with the small-molecule CDK9 inhibitor BAY1251152 revealed that combining it with Cisplatin synergistically enhanced the sensitivity of Caspase-8 depleted cervical cancer cells to Cisplatin under both 2D- and 3D-cell culture conditions." (PMID 36399280, 2022). "CASP8 -652 6 N del + FasR-670A was associated with a reduced risk (P = 0.019, Combined Polymorphism Score (CPS) = −2.34) and CASP8 -652 6 N ins + FasR-1377G was associated with a marginal increased risk (P = 0.047, CPS = 1.99) of cervical cancer among black Africans." (PMID 26458812, 2015). "MiR-21 was up-regulated and regulated multiple signaling pathways in cervical cancer, including TNF-α/caspase-3/caspase-8, PI3K/AKT/mTOR, and RAS/MEK/ERK pathways." (PMID 39060960, 2024). "Additionally, concurrently with the patient data, transcriptome and proteomic profiling of Caspase-8-depleted cervical cancer cell lines (HeLa and SiHa) identified numerous genes with altered expression, including STOM and TGM2, which may boost the propensity for metastasis and invasion." (PMID 36399280, 2022). "In this report, CAR mediates the activation of caspase-8 and increases the mRNA expression level of extrinsic signaling molecules such as FasL, FADDR and TRAIL in C33A cervical cancer cells." (PMID 36712982, 2022). "Here, we report a significant association between disease-related outcomes and pretreatment levels of caspase-8, CDK9 and pCDK9 (Thr 186) expression in a cohort of locally advanced cervical cancer patients treated with definitive CRT and BT." (PMID 36428594, 2022). "Crucially, low Caspase-8 expression in cervical cancer patients leads to poor prognosis, higher CDK9 phosphorylation at Thr186, and increased RNAPII activity in cervical cancer cell lines and patient biopsies." (PMID 36399280, 2022). "Quercetin exerted a synergistic effect on cisplatin-treated cervical cancer cells primarily through downregulating the protein levels of EGFR, MYC, CCND1, and ERBB2 and upregulating CASP8." (PMID 35070983, 2021). "Consistent with this, three apoptotic markers, Fas, FasL and cleaved caspase-8, were increased, suggesting that PEEP inhibits cell proliferation by inducing cell cycle arrest at G2/M phase and triggering apoptosis in cervical cancer cells." (PMID 24245877, 2013). "Work in this direction has primarily attributed the enhanced metastasis or drug resistance in cervical cancer to the regulation of apoptosis or necroptosis in the presence or absence of Caspase-8." (PMID 36399280, 2022). "In summary, our data support the notion that increased pretreatment tumor levels of caspase-8 and CDK9 predict superior clinical responses in cervical cancer patients treated with definitive CRT plus BT, while higher levels of pCDK9 detection are predictive of an impaired clinical response." (PMID 36428594, 2022). "This suggested that the enhanced expression of TGM2 is, at least in part, responsible for the enhanced migration of cervical cancer cells, lacking Caspase-8 expression." (PMID 36399280, 2022). "This suggests that the absence of Caspase-8 expression de-sensitizes cervical cancer cells to CDK9 inhibitors." (PMID 36399280, 2022). "To further explore the roles of Caspase-8 expression in the malignant behavior of cervical cancer cells that might contribute to poor patient prognosis, we used the CRISPR/Cas9 system to generate CASP8-/- HeLa and SiHa cells." (PMID 36399280, 2022). "Since HPV(+) head and neck cancers have driving mutations and cancer pathways in common with cervical cancers, including PIK3CA, FAT1, CASP8, PTEN, etc., comparing the subtypes of HPV(+) HNSCC with those of cervical cancer may reveal additional insights." (PMID 34072836, 2021). "The prognostic impact of PLK3 and its substrate pT273 Caspase 8, however, has not been evaluated in cervical cancer thus far to the best of our knowledge." (PMID 31475104, 2019).